AQP1 (aquaporin 1 (Colton blood group))
Diseases named in the same sentence as AQP1 in open-access papers (continued):
Sharing a sentence is not in itself a finding about the gene and the disease.
neurodegenerative disease (3 papers, 2020 to 2025). A disorder of the central nervous system characterized by gradual and progressive loss of neural tissue and neurologic function. "Among these genes of neurodegenerative diseases, we observed that the NAP1L5 expression was significantly positively correlated with NEUROD6 and NRN1, whereas correlated with negatively CD163, ITPKB, and AQP1." (PMID 36568274, 2022).
retinopathy (2 papers, 2016 to 2019). "Glucose-related hyperosmolarity seems to be able to promote angiogenesis and retinopathy through activation of TonEBP and possibly increasing expression of AQP1 and COX-2." (PMID 26822858, 2016).
benign tumors (1 paper, 2014). "The expression of AQP1, AQP5 and AQP9 are significantly higher in malignant and borderline ovarian tumors than benign tumors and normal ovarian tissues." (PMID 24918928, 2014).
hepatobiliary disorder (1 paper, 2025). A non-neoplastic or neoplastic disorder that affects the liver, bile ducts, and gallbladder. "Additionally, AQPs have been associated with various hepatobiliary disorders, and AQP1 and AQP4 are involved in mechanisms of reabsorption/secretion of water, but there was only a significant increase in AQP3 levels in liver tissue." (PMID 41010898, 2025).
AQP1 also shares sentences with these, for which no sentence is quoted: multiple myeloma (5 papers); salivary gland adenoid cystic carcinoma (5); papillary renal cell carcinoma (4); adenocarcinoma (3); primary open-angle glaucoma (3); urothelial carcinoma (3); acute lung injury (2); allergic asthma (2); autosomal dominant polycystic kidney disease (2); brain diseases (2); breast (2); cerebral oedema (2); diabetic kidney disease (2); ductal carcinoma in situ (2); ependymoma (2); fibrosis (2); hypothyroidism (2); infarct (2); intrahepatic cholangiocarcinoma (2); ischemia reperfusion injury (2); kidney stones (2); leptospirosis (2); obstructive hydrocephalus (2); oligodendroglioma (2); pancreatic ductal adenocarcinoma (2); pharyngeal squamous cell carcinoma (2); pleural mesothelioma (2); Shock (2); acute coronary syndrome (1); acute pancreatitis (1).
A further 80 diseases each share a sentence with AQP1 in 1 paper.